SNHG1 (small nucleolar RNA host gene 1)
Diseases named in the same sentence as SNHG1 in open-access papers (continued):
Sharing a sentence is not in itself a finding about the gene and the disease.
colorectal cancer (continued). "Furthermore, the survival analysis indicated that colorectal cancer patients with higher expression of SNHG1 had a worse prognosis." (PMID 29416759, 2018). "Moreover, the survival analysis indicated that colorectal cancer patients with higher expression of SNHG1 had a worse prognosis." (PMID 29416759, 2018). "We determined whether SNHG1 promoted cell proliferation by repression of miR-145 in colorectal cancer cells." (PMID 29416759, 2018). "Moreover, co-expression of SNHG1 with either p70S6k or E2F3 was analyzed through querying open database ChIPBase v2.0 in TCGA colorectal cancer datasets." (PMID 29416759, 2018). "Mechanistic investigations revealed that SNHG1 could exhibit different regulatory mechanisms in the nucleus and cytoplasm, and it could promote the development of colorectal cancer by regulating CCND2, KLF2 and CDKN2B expression." (PMID 30266084, 2018). "Moreover, SNHG1 knockdown significantly repressed colorectal cancer cells growth both in vitro and in vivo." (PMID 30266084, 2018). "Here, we revealed novel biological effects of SNHG1 in colorectal cancer." (PMID 30266084, 2018). "Importantly, CCND2 silencing impaired SNHG1 overexpression mediated increases in colorectal cancer cells growth and proliferation." (PMID 30266084, 2018). "Furthermore, EZH2 silencing partially impaired SNHG1 overexpression mediated proliferative capacity increase of colorectal cancer cells." (PMID 30266084, 2018). "In addition, multivariate analysis of the three prognosis factors revealed that SNHG1 expression was an independent prognostic biomarker (Hazard ratio [HR] = 2.82; 95% confidential interval [CI] = 1.53–5.18; P = 0.001) for colorectal cancer." (PMID 30266084, 2018). "In addition, we found SNHG1 expression was positively correlated with SP1 expression in colorectal cancer sequencing data from TCGA, and the positive correlation was also observed in our samples." (PMID 30266084, 2018). "We also found SNHG1 promoted cell proliferation via suppression of miR-145 in colorectal cancer." (PMID 29416759, 2018). "RNA pull-down assays also confirmed that SNHG1 could directly bind with AGO2 in colorectal cancer cells." (PMID 30266084, 2018). "SNHG1 expression was correlated with advanced colorectal cancer stage and tumor recurrence." (PMID 29416759, 2018). "In summary, these results suggested that SNHG1 promoted tumor growth of colorectal cancer." (PMID 29416759, 2018). "We also investigated the relationship between SNHG1 expression and colorectal cancer prognosis." (PMID 30266084, 2018). "Thus, the downstream genes of SNHG1 formed a regulatory network to regulate the initiation and progression of colorectal cancer." (PMID 30266084, 2018). "To investigate whether KLF2 and CDKN2B were involved in the SNHG1 induced promotion of colorectal cancer cell growth, we performed rescue assays." (PMID 30266084, 2018). "However, the role of the biology and clinical significance of SNHG1 in the tumorigenesis of colorectal cancer (CRC) has rarely been reported." (PMID 29340086, 2017). "To examine the links between SNHG1 expression and colorectal cancer patients’ prognosis, we performed the Kaplan–Meier analysis and log-rank test to assess overall survival (OS) and progression-free survival (PFS) of patients with colorectal cancer and SNHG1 expression." (PMID 29340086, 2017). "We also elucidated that knockdown of SNHG1 may decrease proliferation, arrest cell cycle, promote apoptosis, limit migration and invasion of colorectal cancer cells." (PMID 29340086, 2017). "Although the role of SNHG1 in colorectal cancer remains largely unknown, our results indicate that it may be important in tumorigenesis and progression." (PMID 28152521, 2017). "Altogether, these data displayed intensified expression of SNHG1 predominantly diminished patients’ survival time and might exhibit crucial role in the prognosis of patients with colorectal cancer." (PMID 29340086, 2017).
colorectal cancer (continued). "In a word, these data exhibited that SNHG1 may function as an oncogene through facilitating colorectal cancer cell growth." (PMID 29340086, 2017). "The multivariate analyses suggested that the high SNHG1 expression could be served as a potential independent prognostic factor for overall survival and progression-free survival of colorectal cancer patients." (PMID 29340086, 2017). "These new findings suggested that SNHG1 may be used as a potential prognostic and therapeutic target of colorectal cancer." (PMID 29340086, 2017). "To explore whether knockdown of SNHG1 alert cell apoptosis, we carried out flow cytometry to analyze the cell apoptosis of colorectal cancer cells when transfected with Si-SNHG1." (PMID 29340086, 2017). "However, the mechanism by which SNHG1 regulates the progression of colorectal cancer (CRC) remains unclear." (PMID 31469189, 2019). "Furthermore, functional studies revealed that SNHG1 could promote cell growth of colorectal cancer cells both in vitro and in vivo." (PMID 29416759, 2018). "Besides, we analyzed SNHG1 expression in human colorectal cancer cell lines." (PMID 30266084, 2018). "We further explored whether SNHG1 could affect colorectal cancer growth in vivo." (PMID 30266084, 2018). "Therefore, we hypothesized that SNHG1 might also work as a sponge to modulate certain miRNAs to promote cell proliferation in colorectal cancer cells." (PMID 29416759, 2018). "In addition, RNA pull-down assays also confirmed that SNHG1 could directly bound with EZH2 in colorectal cancer cells." (PMID 30266084, 2018). "It indicated that SNHG1 might bind miR-145 in colorectal cancer cells." (PMID 29416759, 2018). "In addition, RNA immunoprecipitation (RIP) assay results revealed that SNHG1 and miR-154-5p were significantly enriched in AGO2-containing micro-ribonucleoprotein complexes, suggesting that the AGO2 protein bound to SNHG1 and miR-154-5p directly in colorectal cancer cells." (PMID 30266084, 2018). "Furthermore, we addressed whether target genes of miR-145 could be regulated by SNHG1 in colorectal cancer cells." (PMID 29416759, 2018). "However, the role of SNHG1 in the tumorigenesis of colorectal cancer is still unkown." (PMID 29416759, 2018). "As we hypothesized, SNHG1 knockdown could inhibit colorectal cancer cell proliferation." (PMID 30266084, 2018). "In addition, we proved SNHG1 exhibited an oncogenic role in colorectal tumorigenesis, its expression could affect colorectal cancer cells growth in vivo and in vitro." (PMID 30266084, 2018). "Therefore, we speculated that SNHG1 might serve a principal role in regulating the activation level of the WNT/β-catenin signaling pathway in the colorectal cancer." (PMID 29340086, 2017). "Altogether, our findings demonstrated that lncRNA SNHG1, was high expressed in colorectal cancer tissues and may serve as a tumor oncogene through regulating WNT/β-catenin signal pathway, which provided a candidate diagnostic biomarker and a promising therapeutic target for patients with CRC." (PMID 29340086, 2017). "SNHG1 also functions as a transcriptional regulator to promote the transcription of its neighboring gene SLC3A2 in cis in gastric cancer, colorectal cancer, liver cancer, and lung cancers." (PMID 40510136, 2025). "According to reports, small nucleolar RNA host gene 1 (SNHG1) can affect the development of osteosarcoma by regulating miR-101-3p, miR-326, miR-577 and can influence the proliferation of colorectal cancer cells via miR-154-5p." (PMID 35841022, 2022). "Investigation of molecular pathways reveals down-regulation of miRNA-154-5p by SNHG1 via sponging and EZH2 induction which increases colorectal cancer progression." (PMID 35236381, 2022). "SNHG1, SNHG3, and SNHG20 are predictive biomarkers for neuroblastoma, ovarian cancer, and colorectal cancer, respectively." (PMID 35686101, 2022).
colorectal cancer (continued). "SNHG1, SNHG3, SNHG20 have been separately proved to be a prognostic biomarker in neuroblastoma, ovarian cancer, and colorectal cancer." (PMID 31967298, 2020). "As we expected, RIP results revealed that SNHG1 bound with EZH2, SUZ12 and EED in colorectal cancer cells." (PMID 30266084, 2018). "We next examined the effect of SNHG1 on the cell proliferation to determine the functional role of SNHG1 in of LOVO cells, a colorectal cancer cell line." (PMID 29416759, 2018). "However, the role of SNHG1 in the tumorigenesis of colorectal cancer is still unknown." (PMID 29416759, 2018). "To further validate the prognostic role of SNHG1 in colorectal cancer patients, we carried out the univariate and multivariate survival analysis for OS and PFS in colorectal cancer patients." (PMID 29340086, 2017). "All results above demonstrated a novel correlation between SNHG1 expression and the activation level of the WNT/β-catenin signaling pathway in the colorectal cancer." (PMID 29340086, 2017). "The expression of SNHG1 was 2.5-fold higher in colorectal cancer tissue than non-tumor rectum tissues (*, p<0.05)." (PMID 29416759, 2018). "The TCGA dataset showed that the expression of SNHG1 mRNA is significantly higher in different subtypes of colorectal cancer than that in the non-tumor colorectal tissues (colon or rectum) in these microarray studies (*, p<0.05)." (PMID 29416759, 2018). "The result of qRT-PCR indicated that the colorectal cancer cells exhibited high expression of SNHG1 compared to the normal intestinal mucous cell line (P<0.01)." (PMID 29340086, 2017). "Our data in the present study showed remarkable increase in SNHG1 expression in colorectal cancer tissues compared with adjacent non-cancerous colorectal tissues." (PMID 29340086, 2017). "Multivariate analysis further elucidated that SNHG1 expression could be regarded as a significant independent predictor of OS and PFS in colorectal cancer patients." (PMID 29340086, 2017). "Moreover, we examined the expression of SNHG1 in 82 colorectal cancer tissues and 24 non-tumor rectum tissues through quantitative real-time PCR." (PMID 29416759, 2018). "Recent studies have reported that SNHG1 may stimulate the progression of cancer through modulating the WNT signaling pathway in the NSCLC and WNT signaling pathway is also critical in the initiation, progression and metastasis of colorectal cancer." (PMID 29340086, 2017). "There was literature indicating the upregulation of SNHG1 in thyroid cancer, non-small cell lung cancer (NSCLC), colorectal cancer, but SNHG1 was not studied in bladder cancer." (PMID 36230661, 2022). "Finally, we observed a negative correlation between SNHG1 and KLF2 or CDKN2B expression in colorectal cancer tissues by analyzing RNA sequencing data from TCGA database." (PMID 30266084, 2018).
lung cancer (32 papers, 2016 to 2025). A malignant neoplasm involving the lung. "Moreover, SNHG1 is up-regulated in lung cancer tissue and is associated with poor prognosis." (PMID 33194612, 2020). "Compared to normal bronchial epithelial cells, lung cancer cells exhibited a substantial upregulation of the lincRNA Small nucleolar RNA host gene 1 (SNHG1) expression." (PMID 39912974, 2025). "The SNHG1/miR-101-3p/SOX9/Wnt/β-catenin axis promotes the progression of non–small cell lung cancer." (PMID 40636922, 2023). "Upregulated SNHG1 was demonstrated as a key agent in lung cancer development via the inhibition of miR-101-3p." (PMID 34712495, 2021). "As a newly reported long noncoding RNA, lnc-small nucleolar RNA host gene 1 (SNHG1) was significantly overexpressed in lung cancer cell line than in normal lung epithelial cells; after silencing lnc-SNHG1 expression, the cell proliferation was inhibited." (PMID 33302997, 2020). "HOXA-AS2 acts as an apoptosis repressor in promyelocytic leukemia cells, and SNHG1 has also been suggested as a new biomarker for lung cancer and prostate cancer." (PMID 27966444, 2016). "Importantly, SNHG1 has emerged as a novel oncogenic lncRNA in various cancers, including esophageal, colorectal, prostate, gastric, liver, and lung cancers, inducing cell proliferative, metastatic, migratory and invasive capacities of cancer cells." (PMID 36230661, 2022). "One plausible explanation is that the prognostic value of SNHG1 might be lung cancer histotype dependent." (PMID 32802839, 2020). "In addition, lncRNAs such as DANCR, LINC00336, MNX1-AS1, LINC00673, SNHG4, LEF1-AS1, UCA1 (urothelial carcinoma-associated 1), SNHG1, and PTAR act as ceRNAs for miRNAs and exhibit oncogenic functions in lung cancer cells." (PMID 33412752, 2020). "Latest reports indicated that lncRNA nucleolar small molecule RNA host gene 1 (SNHG1) is located on chromosome 11 and is abnormally overexpressed in a variety of tumor tissue and can accelerate the cell proliferation in lung cancer, liver cancer, gastric cancer, esophageal cancer and PCa cells." (PMID 33194612, 2020). "In addition, the upregulation of SNHG1 in lung cancer positively correlates with both tumor size and tumor-node-metastasis stages." (PMID 31789416, 2020). "SNHG1 could promote NSCLC progression of lung cancer via miR-101-3p/SOX9/Wnt/β-catenin regulatory network and miR-145-5p/ MTDH axis." (PMID 29872497, 2018). "In lung cancer, it's found that SNHG1 could contribute to cancer progression via inhibition of miR-101-3p and activation of Wnt/β-catenin signaling pathway." (PMID 29416759, 2018). "It's also found that SNHG1 could promote cancer progression via inhibition of miR-101-3p and activation of Wnt/β-catenin signaling pathway in lung cancer." (PMID 29416759, 2018). "In addition, we found that SNHG1 expression was ubiquitously increased in 4 lung cancer cell lines (A549, SPC-A1, H23 and NCI-H520) compared to human bronchial epithelial cell line 16HBE (P < 0.05)." (PMID 28147312, 2017). "The SNHG1/miR-101-3p/SOX9/Wnt/β-catenin axis regulatory network might provide a potential new therapeutic strategy for lung cancer treatment." (PMID 28147312, 2017). "In the ceRNA network of lung cancer, CCNE1 interacts with SNHG1 and PVT1 via mir-497, which is known to down-regulate cyclin E1 to inhibit the growth of lung cancer cells." (PMID 38978021, 2024). "For AAs, the most accurate prediction for lung cancer was achieved by combining three lncRNAs (MALAT1, PVT1, and SNHG1) with smoking pack-years." (PMID 38791954, 2024). "We filtrated expression of lncRNAs in lung cancer cells after sevoflurane treatment, namely PCAT6, UCA1, SNHG1, CCAT2, and found that the level of PCAT6 was significantly suppressed after sevoflurane administration." (PMID 33987473, 2020). "In vitro experiments showed that high SNHG1 expression was related to larger tumour sizes and advanced TNM stages, and down‐regulation of SNHG1 suppressed cell proliferation in lung cancer." (PMID 29575772, 2019).
lung cancer (continued). "Droplet Digital PCR (ddPCR) was used for quantification of the genes (miRs-21, 210, 486-5p, SNHG1, RMRP, FUT8, and POFUT1) in plasma of a development cohort of 64 lung cancer patients and 33 cancer-free individuals." (PMID 29872497, 2018). "Small nucleolar RNA host gene 1 (SNHG1) is a widely and highly expressed lncRNA in a variety of diseases, and is considered a gene that regulates tumor progression, such as in lung cancer." (PMID 35656102, 2022). "We have found that expression levels of SNHG1 and RMRP are reliably measured in plasma, and the lncRNAs may provide cell-free circulating biomarkers for lung cancer." (PMID 32294932, 2020). "Particularly, H19, NEAT1, SNHG1, and TUG1 were significantly more expressed in lung cancer patients from both AA and WA lung cancer patients compared to those without cancer." (PMID 38791954, 2024).
prostate carcinoma (31 papers, 2016 to 2025). A carcinoma that arises from epithelial cells of the prostate gland. "Nevertheless, the underlying mechanism between SNHG1 and RBPs in tumors remains to be explored, especially in prostate cancer (PCa)." (PMID 33542227, 2021). "Silencing SNHG1 or EZH2 is associated with decreased viability of prostate cancer cells." (PMID 35317831, 2022). "Knockout of SNHG1 significantly inhibited the proliferation, migration, and invasion, which promoted apoptosis of prostate cancer cells." (PMID 39716349, 2025). "In prostate cancer, SNHG1 promotes EMT processes by competitively binding to hnRNPL, preventing E-cadherin translation." (PMID 38331968, 2024). "We determined endogenous SNHG1 levels in a panel of prostate cancer cell lines and correlated expression to measured docetaxel IC50 values." (PMID 37464317, 2023). "Further investigation of this is clearly warranted, given the importance of the androgen receptor in prostate cancer progression and treatment, and that SNHG1 levels dramatically affect quiescence and cell cycle as we have shown here." (PMID 37464317, 2023). "Overall, these results indicate SNHG1 has complex roles in prostate cancer, as it stimulates cell cycle entry and disease progression, but sensitizes cells to docetaxel treatment." (PMID 37464317, 2023). "In vitro analysis of prostate cancer cell lines showed SNHG1 expression correlated with a quiescent versus proliferative phenotype." (PMID 37464317, 2023). "Data in prostate cancer has shown SNHG1 is regulated by dihydrotestosterone treatment, and there is a correlation between high SNHG1 expression and pathological stage, Gleason score, and time to biochemical recurrence." (PMID 37464317, 2023). "Here we observe and characterize the biological effects of SNHG1 on prostate cancer cells through selectively suppressing its expression using RNAi." (PMID 37464317, 2023). "As we show here, SNHG1 is involved in prostate cancer outcome, and can have an outsized effect on cellular quiescence and docetaxel response." (PMID 37464317, 2023). "Knockdown of SNHG1 in multiple prostate cancer cell lines prevented cells from exiting G0, or suppressed cycling cells such that they entered G0, as determined by expression of the quiescent cell marker p27." (PMID 37464317, 2023). "Elucidation of the molecular mechanism of these effects is important because as we have shown, SNHG1 levels correlate with prostate cancer metastasis and impact clinical outcome." (PMID 37464317, 2023). "In this study, we investigated the role of a long non-coding RNA (lncRNA), SNHG1, on cell proliferation, quiescence, and sensitivity to docetaxel as a potential factor important in prostate cancer biology." (PMID 37464317, 2023). "SNHG1 was reported to play an oncogenetic role in prostate cancer via the ceRNA networks of miR-199a-3p/CDK7 and miR-377-3p/AKT2." (PMID 35864871, 2022). "The role of SNHG1 in prostate cancer is suggested to be tumor-promoting, so that SNHG1 can increase metastasis via EMT induction." (PMID 35317831, 2022). "For example, silencing the expression of SNHG1, reducing the binding effect, increasing the expression of miR-199a-3p, and inhibiting the proliferation of prostate cancer cells." (PMID 30728054, 2019). "Moreover, SNHG1 is commonly described as an oncogenic lncRNA overexpressed in many cancers, including colorectal, liver, lung and prostate cancers (Thin, Tu, & Raveendran." (PMID 36194366, 2023). "Furthermore, there is a small, but significant negative correlation between SNHG1 expression and docetaxel IC50 in a panel of prostate cancer cell lines, which is consistent with our data indicating reduced apoptosis after SNHG1 knockdown." (PMID 37464317, 2023). "Furthermore, SNHG1 expression correlates with the quiescent versus cycling state of unmanipulated prostate cancer cells." (PMID 37464317, 2023). "RNAi and prostate cancer cell lines were utilized to investigate SNHG1 in vitro." (PMID 37464317, 2023).